SETD2 (SET domain containing 2, histone lysine methyltransferase)
Diseases named in the same sentence as SETD2 in open-access papers (continued):
Sharing a sentence is not in itself a finding about the gene and the disease.
tumor (continued). "Mutations or functional loss of SETD2 leads to dysfunctional tumor proteins and further tumorigenesis, progression, chemotherapy resistance and unfavorable prognosis." (PMID 37989747, 2023). "Blocking oxidative respiration and mTORC1 signaling abrogates the high rates of tumor cell proliferation and tumor growth specifically in SETD2-deficient tumors." (PMID 36899051, 2023). "Consistent with the reported findings, we showed that Setd2 deficiency accelerated the initiation of KrasG12D-driven lung tumorigenesis, increased tumor burden, and significantly reduced mouse survival." (PMID 36810256, 2023). "This crucial role of SETD2 in lipid metabolism is further validified with in vivo intervention that tumor symptom caused by Setd2 knockout is mitigated by myriocin, a selective inhibitor for sphingomyelin biosynthesis." (PMID 37989747, 2023). "SETD2-deficient tumors were particularly sensitive to rapamycin treatment, which had a similar suppressive effect on tumor growth as phenformin which inhibits both mitochondrial complex I and mTORC1 signaling." (PMID 36899051, 2023). "Our results indicate that more comprehensive co-analyses of SETD2 mutation and H3K36me3 levels are warranted in future studies, and will likely be essential to fully understand their interplay with tumor phenotypes and patient outcome." (PMID 37120552, 2023). "In-depth investigations of the role of SETD2 in the process of tumor formation and development and the underlying mechanism are of great significance for the diagnosis, treatment and prevention of tumors." (PMID 37359376, 2023). "A comparison of global methylation between the normal and tumor groups stratified by SETD2 mutation status shows significant differences among most groups." (PMID 37120552, 2023). "We then linked 5mC variability to entropy and found that tumor 5mC entropy was strongly linked to clinical parameters including tumor grade and metastasis, and that SETD2 wt tumors had greater 5mC entropy than SETD2 mutant tumors." (PMID 37120552, 2023). "In summary, our mechanistic elucidation of the tumor suppressor function of SETD2 has identified therapeutic vulnerabilities and actionable therapeutic targets for the treatment of SETD2-deficient cancers." (PMID 36810256, 2023). "In summary, our study revealed that Setd2 deficiency directly enhanced the recruitment and reprogramming of neutrophils, thereby facilitating immune escape and fostering tumor progression by inhibiting cytotoxicity of CD8+ T cells." (PMID 36453584, 2023). "SETD2 loss appears to create a permissive epigenetic landscape for the cooperating driver oncogenes to amplify their transcriptional output for tumor initiation in a context-dependent manner." (PMID 36810256, 2023). "Higher secretion of TGF-β1 in GBM cells derived from patients carrying the SETD2 mutation led to an increase in activated tumor-associated microglia which fueled tumor progression." (PMID 37205197, 2023). "Tumor symptom caused by Setd2 knockout is relieved by myriocin, a selective inhibitor of serine-palmitoyl-transferase and sphingomyelin biosynthesis." (PMID 37989747, 2023). "The H3K36me3 methyltransferase SETD2 is generally proposed to function as a tumor suppressor, and loss-of-function mutations in SETD2 occur in a broad spectrum of human malignancies." (PMID 37051671, 2023). "In this work, we examined epigenetic level ITH and defined its relationships with pathologic features, aspects of tumor biology, and SETD2 mutations." (PMID 37120552, 2023). "This is also of particular clinical relevance as depletion of SETD2 and H3K36me3 is associated with more aggressive tumours and worse prognosis." (PMID 37528416, 2023). "SETD2 loss of function is usually subclonal, meaning that it is only present in some cells within a single tumor." (PMID 37887570, 2023). "SETD2 is frequently mutated in a wide range of tumor types, suggesting that SETD2 functions as a tumor suppressor." (PMID 37359376, 2023).
tumor (continued). "Yet, the underlying mechanisms of SETD2 gene mutations or loss of function leading to the corresponding dysfunction of tumor tissue proteins remain largely unexplored." (PMID 36713412, 2022). "The frequent mutation of SETD2 in multiple types of cancer suggests that SETD2 is a tumor-suppressor gene." (PMID 35661267, 2022). "Strikingly, contrary to its role as a tumor suppressor, excessive SETD2 results in the upregulation of cell cycle-associated pathways." (PMID 36035998, 2022). "SETD2 loss in ccRCC has also been correlated with defects in mRNA splicing, including in known tumor-suppressor genes." (PMID 35661267, 2022). "In the analysis of clinical sample, mutations in SETD2 led to the enrichment of tumor cell surface mutation-specific neoantigens, such as mutational load (TMB) microsatellite instability-high (dMMR/MSI-H)." (PMID 36713412, 2022). "An analysis of the intratumor heterogeneity of several primary ccRCC tumors furthermore revealed that independent SETD2 mutations tend to arise in distinct sections within a single tumor." (PMID 35661267, 2022). "The formation of an NFR upstream from the 5′ exon/intron boundary led to DNA hypomethylation and the depletion of H3K36me3 in SETD2-deficient tumours." (PMID 36354002, 2022). "The tumour suppressor genes SETD2 and PBRM1 were the most frequently mutated genes in our cohort (mutated in 62% and 57% of the patients, respectively)." (PMID 35231161, 2022). "This indicates that α-tubulin methylation is disproportionally sensitive to loss of one SETD2 allele (compared to H3K36me3) and that mitotic defects caused by impaired tubulin methylation are likely early drivers in ccRCC tumor development." (PMID 35661267, 2022). "Loss of SETD2 function has been investigated in several human tumours, including GI stromal tumours, renal cell carcinoma, pancreatic ductal adenocarcinoma (PDAC), prostate cancer, breast cancer, leukaemia and high‐grade gliomas." (PMID 33949020, 2021). "In other diseases, SETD2 is thought to serve as a tumor suppressor, as mutations can hamper DNA repair mechanisms and increase mutation rates." (PMID 35127532, 2021). "Based on these findings, they decided to run further analyses for Setd2 in human tumor samples and have come across a correlation between loss of Setd2 and poor survival." (PMID 34781949, 2021). "SETD2 mutations occurred in a small subset of most tumor types, and the mutant frequencies differed significantly across various tumors (P < 0.001)." (PMID 34127768, 2021). "As mutations in SETD2 continue to be identified in a growing list of tumor types, it will be important to discern the relative roles of histone versus tubulin methylation in contributing to the underlying mechanisms of particular cancer phenotypes." (PMID 34157286, 2021). "In summary, our data reveal that SETD2 mutation is correlated with higher tumor mutation burden and MSI, and more immune activities in cancer." (PMID 34127768, 2021). "A recent systematic drug sensitivity screening shows that loss of SETD2 sensitized tumor cells to CDK7 inhibitor, and BAP1 depletion confers vulnerability to inhibitor of DNMT150." (PMID 33423045, 2021). "Loss-of-function mutations in the SETD2 tumor suppressors that encodes for an H3 histone H3K36 lysine N-methyltransferase, are frequently found in MPM." (PMID 35069219, 2021). "Authors concluded that Setd2 can potentially act as a tumor suppressor gene in lung adenocarcinoma, since its deficiency promoted shifting of the tumor grade." (PMID 34781949, 2021). "H3K36me3 reduction due to decreased expression or inactivity mutation of SETD2 is observed frequently in various cancers, so SETD2 is generally identified as a tumor suppressor." (PMID 34715919, 2021).
tumor (continued). "Recent reports have emphasized the tumor-suppressive role of H3K36me3 in renal cancer especially, where the gene coding for the SETD2 histone methyltransferase is often deleted or mutated." (PMID 33023640, 2020). "Mutation, or functional loss, of the SETD2 gene produces dysfunction in corresponding tumor tissue proteins, leading to tumorigenesis, progression, chemotherapy resistance, and unfavorable prognosis, suggesting that SETD2 possibly acts as a tumor suppressor." (PMID 32231741, 2020). "Our data demonstrated that SETD2 expression was significantly associated with tumor size (P = 0.012) and tumor stage (P = 0.027) of the patients." (PMID 33223508, 2020). "Recently, SETD2 has been clarified to play a suppressive role in CRC 76, and inactivation of SETD2 induces tumor malignant potential and increases susceptibility to tumorigenesis." (PMID 32231741, 2020). "Consistent with its association with tumor-suppressive phenotype, the reintroduction of SETD2 FL led to a decrease in cell proliferation." (PMID 33023640, 2020). "The expression levels of SETD2 and H3K36me3 is associated with the tumor size, clinical stage and risk of carcinoma-related death, suggesting the worse prognosis in ccRCC patients with or without metastasis 57,64,65." (PMID 32231741, 2020). "To determine if the tumor growth capacity of SETD2 deficient ccRCC-derived cell lines was similarly dependent on PI3Kβ, we utilized 3-D spheroid cultures in Matrigel to allow cells to self-assemble into organotypic structures (spheroids)." (PMID 30774762, 2019). "As the majority of cancer patients present with heterozygous mutations in SETD2, it is conceivable that SETD2 functions as a haplo-insufficient tumor suppressor, while its homozygous loss impedes disease progression." (PMID 30818762, 2019). "As a number of different missense mutations occurring throughout the SETD2 gene have been seen in CNS tumors, as well as in other tumor types, the role of individual missense mutations in tumorigenesis is unclear." (PMID 30419952, 2018). "Loss of SETD2 and subsequent decrease of H3K36me3 led to significant tumor-promoting consequences, accelerating both early- and late-stage lung adenocarcinoma tumors in mice." (PMID 30002791, 2018). "In contrast, for the tumors with nonsense or frameshift mutations in SETD2, fewer concurrent PM were detected, and in one tumor (#3), the PM in SETD2 was the only mutation detected on the NGS panel, at a VAF of 23%." (PMID 30419952, 2018). "Immunohistochemistry shows a decrease in H3K36me3 in tumor with SETD2 mutations, implicating epigenetic pathways in tumor biology." (PMID 30419952, 2018). "SETD2 is typically associated with tumor suppressor activity and is often mutated in several cancer types." (PMID 30312361, 2018). "We excluded tumours with mutated SETD2 gene as this mutation was known to be associated with altered epigenetic phenotype." (PMID 30006568, 2018). "For ARID1A and SETD2, the statistically significant associations between marker losses and tumor stages would have been missed if truncal loss analysis were not performed." (PMID 28445125, 2017). "SETD2 mutations were significantly associated with global DNA hypermethylation in all three tumor types." (PMID 26646321, 2016). "In SETD2-mutated tumours H3K36me3 had IHC scores ranging from 0 to 12 (median score 1) being either undetectable or very weakly expressed (scores 0 to 2) in 10/12 evaluable cases." (PMID 27600764, 2016). "Functionally, global DNA hypermethylation events occur in large DMRs conserved across multiple tumor types with SETD2 mutations and result in up-regulation of lowly expressed genes that collectively appear to drive cells toward a more undifferentiated state." (PMID 26646321, 2016). "Using whole exome sequencing and H3K36me3-staining of tissue sections, they identified different SETD2 mutations in different regions of the same primary tumor in three cases." (PMID 27191891, 2016).
tumor (continued). "SETD2 mutation or down-regulation occurs across a broad spectrum of tumor types although in many of these its frequency is relatively low (< 10%) making detailed analysis of its effects feasible only with large datasets." (PMID 26646321, 2016). "Consistent with its postulated role as a tumour suppressor, our data highlight SETD2 aberration as a recurrent, early loss-of-function event in CLL pathobiology linked to aggressive disease." (PMID 27282254, 2016). "The Histone-lysine N-methyltransferase SETD2 gene on chromosome 3p21.31 was mutated in 13/15 (86%) tumours." (PMID 27600764, 2016). "The high frequency of inactivating SETD2 mutations in ccRCC points to a tumor-suppressor-like function of this gene." (PMID 27191891, 2016). "In a study including 185 ccRCC patients, SETD2 mutations were significantly associated with advanced tumor stage (P = 0.02)." (PMID 27191891, 2016). "Sanger sequencing confirmed each SETD2 variant in the tumour material and in two cases with germline material available, the variants were somatically acquired." (PMID 27282254, 2016). "The loss of SETD2 impairs DNA repair and enhances genomic instability, supporting its tumour suppressor role." (PMID 27282254, 2016). "The highlight of our study is the discovery of frequent alterations of the tumour suppressor SETD2 gene by loss-of-function mutations and/or loss of the corresponding 3p.21 locus in the majority of the cases (14/15)." (PMID 27600764, 2016). "The high frequency of SETD2 alterations and the mutational spectrum strongly supports the tumour suppressor role of SETD2 in EATL-II." (PMID 27600764, 2016). "Further studies on the potential functional consequences of SETD2 missense mutations are required to establish their role in tumor development and/or progression." (PMID 27191891, 2016). "This suggested that loss of SETD2 can be a late event that provides a selective advantage to tumor cells." (PMID 27191891, 2016). "SETD2 loss showed a more dramatic increase with increasing tumor stages; 5% (4%), 13% (4%), 15% (6%), and 25% (10%) from stages I to IV, respectively." (PMID 27764136, 2016). "We specifically detect parallel evolution of multiple SETD2 mutations within different sub-regions of the same tumour." (PMID 25790038, 2015). "Using a monoclonal antibody against H3K36me3, we were able to distinguish SETD2-deficient from SETD2-proficient tumor xenografts by immunohistochemistry (IHC)." (PMID 26602815, 2015). "They discovered convergent tumor evolution since a given tumor contained different mutations of the same genes, SETD2, KDM5C and PTEN, depending on its spatial orientation." (PMID 25411563, 2014). "We and others have reported the associations of PBRM1, SETD2, BAP1, and KDM5C mutations with advanced stage, grade, and tumor invasiveness, and discovered that SETD2 and BAP1 mutations are associated with lower cancer-specific survival rates." (PMID 25124064, 2014). "Future studies may also benefit from a more granular collection of pathologic characteristics to more fully study the tumor biology related to the SETD2 mutation status." (PMID 41228333, 2025). "Studies have linked SETD2 mutations to both human and canine OS, suggesting it may contribute to tumor development." (PMID 40507962, 2025). "Notably, while H3K36me2-generating enzymes like NSD2 and NSD3 promote oncogenesis when mutated or overexpressed, SETD2 is a potent tumor suppressor frequently mutated in clear cell renal cell carcinoma (ccRCC) and several other cancers." (PMID 40462961, 2025). "This included MVD and GLUT1 expression in tumors with mutated VHL, mTOR phosphorylation in tumors with activating mutations in PI3K/AKT/mTOR pathway genes, H3K36me3 status and mutations in SETD2 and, lastly, the tumor cell proliferation rate and presence of multiple driver gene mutations." (PMID 40352587, 2025). "SETD2 functions as a tumor suppressor, and its loss promotes cancer progression and metastasis." (PMID 40959108, 2025).
tumor (continued). "Distinct subclonal SETD2 mutations occur in spatially separate regions of ccRCC, indicating selection for SETD2 inactivation, yet the advantage this mutation confers to cancer cells and/or the tumor microenvironment (TME) remains unclear." (PMID 37418588, 2024). "In the predicting model, TMB is a key contributor, and patients with SETD2 mutations may have higher TMB indicating the increasing likelihood of generating immunogenic tumor neoantigens recognized by the host immune system." (PMID 38843391, 2024). "Additionally, the TCPA protein database and TCGA PRAD GSEA implicated SETD2 in pathways linked to tumor progression, chemoresistance, and adverse prognosis, including the AMPK, cAMP, and PI3K-Akt signaling pathways." (PMID 38611113, 2024). "A minor proportion of cancer cells with a mutation in SETD2 may secrete factors into the TME that favor growth or invasion of the tumor collectively." (PMID 37418588, 2024). "The combined effect of SETD2 overexpression with ERG gain or PTEN loss may lead to more aggressive tumor behavior, including increased metastatic potential and resistance to treatment, resulting in poorer prognostic outcomes for patients." (PMID 38611113, 2024). "Observations from ITH studies in ccRCC revealed that SETD2 mutations are independently acquired in multiple regions of individual tumors, indicating that loss of H3K36me3 actively confers some advantage onto tumor cells." (PMID 37418588, 2024). "The competitive and/or cooperative interactions between SETD2‐deficient cells and other tumor subclones that result from ITH, and how these interactions impact growth properties of neighboring cancer cells or the tumor as a whole through non‐cell autonomous mechanisms remains to be determined." (PMID 37418588, 2024). "Collectively these results suggest that ribosomal- and mitochondrial-biosynthetic pathways are activated in SETD2-deficient tumors and may be responsible for driving increased tumor cell proliferation." (PMID 36899051, 2023). "Furthermore, SETD2 mutation was associated with the immunotherapy response rate in multiple tumor types." (PMID 37031459, 2023). "Of note, in our study, tumor symptom caused by Setd2 knockout was relieved by myriocin." (PMID 37989747, 2023). "Notably, all Setd2fl/fl mice remained healthy at 1 year after adeno-Cre infection, indicating that Setd2 deficiency alone is insufficient for tumor initiation." (PMID 36810256, 2023). "However, in two large pan-cancer retrospective studies, which enrolled 451 and 375 SETD2-mutated tumors, respectively, SETD2 loss of function correlated with a higher tumor mutation burden and a better response to ICI immunotherapy." (PMID 37887570, 2023). "A SETD2 variant was detected in 75% of tumours from one patient (D)." (PMID 36882706, 2023). "In this way, mis-regulated splicing of tumor-suppressor genes in SETD2 deficient tumors may contribute to tumor progression." (PMID 35661267, 2022). "The predominantly metastatic tumours in our cohort contained more frequent mutations in several genes such as SETD2, APC, KDM5C, HIF1A, RBM10, TRAK1 and FBXW7, while we detected lower mutation rates in VHL compared to the primary tumours analysed in the TCGA study." (PMID 35231161, 2022). "Moreover, tumor cells with loss of H3K36me3 due to mutation in SETD2, the gene that encodes a histone lysine methyltransferase, or mutation in histone H3 itself showed HR, NHEJ, and MMR impairment and sensitivity to WEE1, CHK, or ATR inhibitors." (PMID 36499000, 2022). "In addition, SETD2 inactivating mutations are more frequently found in advanced stage ccRCC tumors and correlate with increased tumor recurrence and worse cancer-specific survival." (PMID 35661267, 2022).